TLR9 (toll like receptor 9)
Diseases named in the same sentence as TLR9 in open-access papers (continued):
Sharing a sentence is not in itself a finding about the gene and the disease.
cancer (continued). "Taken together, these results demonstrate that oxidized mtDNA-STING signaling but not TLR9 signaling or IL-1β secretion is involved in the protective antitumor immunity induced by the irradiated cancer cell vaccine." (PMID 32398808, 2021). "Molecular studies showed that TLR9 signaling, negatively involved in MDSC-mediated cancer metastasis, was highly repressed and that exogenous Lf administration was able to revert the phenotype by enhancing TLR9 pathway as well as by inducing MDSCs differentiation and apoptosis." (PMID 32183434, 2020). "This novel regulatory mechanism involving TLR9 in the posttranscriptional modification of PARP1 and the level of PARG may contribute to the development of a cancer therapy involving the PARP or PARG signaling pathway." (PMID 32483468, 2020). "Thus, DNA-sensors TLR9 and AIM2 perform opposite functions to entail either survival (TLR9) of death (AIM2) of the cancer cells." (PMID 31205871, 2019). "In the current work we have addressed this open question in the context of a renewed interest in cancer cell metabolism and identified CAT-1 as the only arginine importer in both, CLL cell lines as well as PB CLL cells with a strong induction upon TLR9 activation in the latter." (PMID 31824848, 2019). "Similarly, some other TLR9 agonists such as CYT003, EMD 1201081, and GNKG168 have been tested clinically against various cancers." (PMID 31480568, 2019). "Here, we describe a role for TLR9 in cell cycle regulation in viral and in non-viral-induced cancers." (PMID 27454079, 2016). "Agonists, such as CpG oligodeoxynucleotides (CpG) that bind to Toll Like Receptor 9 (TLR9), have been evaluated as therapeutic adjuvants in cancer vaccine strategies and have shown efficacy in inducing antigen-specific adaptive antitumor immune responses in animal models." (PMID 26829221, 2016). "At the present time, solid evidence supporting the use of TLR-9 agonists for the treatment of cancer patients is still lacking." (PMID 28548068, 2014). "TLR9 is a cellular DNA receptor which, based on our observations, appears to regulate cancer cell invasion in the absence of exogenously added DNA ligands." (PMID 24273604, 2013). "Results revealed that 124 (66.7%) of the tumors were strongly positive, 59 (31.7%) were weakly positive and 3 (1.6%) were negative, for cytoplasmic TLR9 immunostaining in cancer cells." (PMID 23761830, 2013). "Evaluation revealed that 124 (66.7%) of the tumors were strongly positive, 59 (31.7%) were weakly positive and 3 (1.6%) were negative for cytoplasmic TLR9 immunostaining in cancer cells." (PMID 23761830, 2013). "C. jejuni activated avian, but not human TLR9 transiently expressed in a transfected cancer cell line in vitro." (PMID 21698299, 2011). "As a receptor for CpG ODN, TLR9 play a key role in tissue repair and cancer progression, it was demonstrated that CpGs stimulated the invasion of TLR9+ cancer cells, but not TLR9- cancer cells." (PMID 20696081, 2010). "In tumors, cancer cells exhibited high expressions, especially of TLR4 and TLR9." (PMID 21129170, 2010). "It is, therefore, critical that we continue to understand the biology of TLR9 as, for instance, the differential endosomal biology between cancer and noncancerous cells could be exploited for this purpose." (PMID 38201300, 2024). "In smokers, CLEC4C, LILRA4, and TLR9 levels were consistently higher than those in non-smokers; however, statistical significance was not reached, probably because of the immense proportion of epithelial components, including cancer cells (data not shown)." (PMID 37435086, 2023).
cancer (continued). "Therefore, reduced levels of LINC01003 might play a crucial role in the dysregulated inflammation that could occur in response to TLR9 stimulation, particularly in situations where RBC-TLR9 levels are reduced due to treatments or cancer." (PMID 38203297, 2023). "Additionally, TLR9, TLR8-AS1, and TLR12P were infrequently detected in these cancer tissues." (PMID 35801728, 2022). "Similarly, a mouse-specific CpG ODN has been evaluated in murine tumor model, however a similar human TLR9-selective CpG ODN has not been previously investigated for cancer peptide vaccines in mice." (PMID 35003132, 2021). "Above all, we can see that no matter whether the function of TLR9 is pro- or anti-cancer, it is important in the immunotherapy of cancer." (PMID 33469538, 2020). "Recent studies suggest that DNA sensors such as AIM2, TLR9, DHX9, DHX36 and adaptor STING may have roles in CRC development, and the other DNA sensors such as DDX41, DDX60, IFI16, and DAI participate in the development of other types of cancers." (PMID 31949493, 2020). "30, 40 In conclusion, in addition to escaping immune recognition, we have shown that the deregulation of TLR9 in viral and non-viral induced cancer may also favor carcinogenesis." (PMID 27454079, 2016). "Interestingly, activation of TLR9 with ODN and ODN + HMGB1 showed highly significant proliferation promoting effects in MIAPaCa-2 (155% and 145%, p < 0.0001), BxPC-3 (147% and 133%, p < 0.0001), and PaCaDD135 cancer cells (112% and 118%, p < 0.005)." (PMID 27941651, 2016). "In present study, we further demonstrated that TLR9 signaling could enhance the expression of HuR through Akt pathway, which ultimately reduce the expression of miR-7, suggesting that PI3K/Akt pathway was important for the expression of HuR in cancer cells." (PMID 24004462, 2013). "Finally, various viral infections have been shown to downregulate TLR9 expression in normal tissues, although this has not yet been demonstrated in cancer cells." (PMID 23761830, 2013). "Furthermore, a selected set of Campylobacter strains did not activate human TLR9 expressed in a transfected human cancer cell line." (PMID 21698299, 2011). "Here, we developed S-540956, a novel TLR9-agonistic adjuvant consisting of B-type CpG ODN2006 (also known as CpG7909), annealed to its complementary sequence oligodeoxynucleotide (ODN) conjugated to a lipid; it could target both a cancer peptide antigen and a CpG-adjuvant in the draining LNs." (PMID 35003132, 2021). "Currently, only two TLR agonists are FDA approved for cancer: Bacillus Calmette-Guerin (acting as a TLR2/4 and TLR9 agonist) against non-muscle-invasive bladder cancer and imiquimod, a TLR7 agonist for superficial basal cell carcinoma." (PMID 41086813, 2025). "Because of the TLR3-, TLR7-, and TLR9-mediated CD8+ T-cell response in TH1 mode, agonists specific to these TLRs are used for cancer nonvaccines." (PMID 31480568, 2019). "Cancer cells express well-known PRRs—DNA sensors, such as absent in melanoma 2 (AIM2) and toll-like receptor 9 (TLR9)." (PMID 31205871, 2019). "Moreover, the most adequate timing for TLR-9 agonist administration is likely to be not yet determined, as an appropriate period between TLR-9 agonists and chemotherapy administration may be necessary to avoid the suppression of anti-cancer immune response by cytotoxic agents." (PMID 28548068, 2014). "TLR7 was found overexpressed in the nuclear membrane and nuclei of cancer cells (a novel localization discovered) having higher levels in HPV-positive specimens, unlike TLR9 that showed reduced expression levels in HPV-positive samples compared to HPV-negative." (PMID 29854832, 2018).
bacterial infection (47 papers, 2010 to 2025). "Of particular relevance, bacterial infections that are commonly treated with antibiotics can initiate immune responses via bacterial DNA, which functions as a pathogen-associated molecular pattern that activates Toll-like receptor 9 (TLR9) following endosomal translocation." (PMID 40839560, 2025). "In pneumonia models, bacterial infection activated type I IFN signaling via TLR9 in dendritic cells." (PMID 40525851, 2025). "TLR9 presence on the surface of red blood cells was assessed using flow cytometry in both healthy individuals and patients with bacterial infections." (PMID 40046178, 2024). "Upon analyzing TLR9 expression in 64 patients with bacterial infection, we observed the average expression of TLR9 on the surface of patients’ red blood cells was 5.45%, which was less than that of healthy people (p < 0.001)." (PMID 40046178, 2024). "We detected the expression of TLR9 on the surface of red blood cells after co-culturing the plasma of patients with bacterial infection with healthy red blood cells for 24 h." (PMID 40046178, 2024). "They assessed several SNPs of TLR4 and TLR9 genes with respect to different phenotypes such as bacterial infection, gingival inflammation/recession, and OSCC." (PMID 38606218, 2024). "CpG exposure leads to glial reactivity, through toll-like receptor 9 (TLR9), and memory deficits in murine models, implicating the significance of peripheral bacterial infections and their potent impact on the brain." (PMID 37649972, 2023). "TLR2- and TLR9-independent mechanisms promote osteoclastogenesis in RANKL-primed precursors during intracellular bacterial infection." (PMID 36226943, 2022). "TLR9 is known to recognize bacterial DNA and plays a role in an innate immune response against bacterial infection." (PMID 36194127, 2022). "The action of synthetic CpG is to mimic a stimulation by bacterial infection and then interact with Toll-like Receptor 9 (TLR-9)." (PMID 34696284, 2021). "The phosphorylated DNA aptamer against toll-like receptor 9 (TLR9) is an intracellular TLR9 agonist that activates TLR signaling pathways to elicit local or adaptive immune responses against bacterial infection." (PMID 34522231, 2021). "TLR9 is typically considered as a sensor for CpG DNA, which is relevant to viral and bacterial infections." (PMID 32967351, 2020). "Previously, our laboratory has demonstrated the utility and effectiveness of intranasal delivery of potent innate immune activators such as liposome-TLR9 complexes for prevention of mortality due to lethal viral or bacterial infections." (PMID 32584899, 2020). "Activation of platelets with thrombin induces an important modulation of TLR1, TLR6, and TLR9 during vascular lesions potentially mediated by bacterial infection." (PMID 31781518, 2019). "It is possible therefore that MSRV/HERV-W activation is induced either directly by TLR9 activation as in the presence of a bacterial infection or by pro-inflammatory cytokines expressed by CpG-activated B cells." (PMID 30740110, 2018). "It is well documented that TLR9 has evolved to recognize bacterial infections by the frequently unmethylated CpG DNA." (PMID 29378591, 2018). "TLR9 activation provides protection against bacterial infections and Heme oxygenase-1 (HO-1) is known to enhance host innate immunity against bacterial infections." (PMID 28052108, 2017). "Polymorphonuclear neutrophils (PMNs) are the first line of defense in bacterial infection and express surface Toll-like receptor 9 (sTLR9)." (PMID 27057095, 2016). "Intracellular TLR9 activates innate immune defenses against viral and bacterial infection and plays a role in the pathogenesis of NASH." (PMID 23861927, 2013). "TLR4 and TLR9 recognise products of bacterial infection and little is known about human primary BEC IFN responses to TLR4 and TLR9 ligands in normal healthy subjects or in asthmatic subjects." (PMID 23824215, 2013).
bacterial infection (continued). "Furthermore, the activation of TLR9 by bacterial infections in zebrafish, where TLR9 identifies CpG ODNs, showcases an additional immune activation layer aiding in bacterial threat management." (PMID 39483482, 2024). "However, the average expression of TLR9 on red blood cell surfaces in patients with bacterial infection was 5.45%, which was lower than that in healthy people (p < 0.001)." (PMID 40046178, 2024). "We speculated whether the disparity in TLR9 expression on the surface of red blood cells between healthy individuals and patients with bacterial infection could be attributed to increased mtDNA binding, potentially obstructing the detection sites of TLR9." (PMID 40046178, 2024). "To explore this hypothesis, we co-cultured plasma from patients with bacterial infection with healthy red blood cells for 24 h and subsequently assessed the expression of TLR9 on the red blood cell surface." (PMID 40046178, 2024). "Finally, progranulin binds to both TLR9 and CpG oligonucleotides (CpG-ODNs) in immune cells and endosomes, favoring TLR9 and CpG-ODNs interaction and potentiating the innate immune response to bacterial infections." (PMID 36980592, 2023). "However, very little information on the interrelationship of endosomal TLRs, mainly TLR9, and this form of cell death in bacterial infection has been established." (PMID 36194127, 2022). "Specifically, TLR9 constitutively associates with Cav-1 and facilitates MyD88-mediated TRAF3 and IRF3 signal transduction, providing the observed InP effect in fatal doses of bacterial infection." (PMID 31534550, 2019). "Thus, TLR9 seems to play a differential role in resistance to MRSA in the context of secondary bacterial infection post-IAV." (PMID 30682165, 2019). "Especially important for bacterial infections are TLR2, TLR4 and TLR9: TLR2 is activated by bacterial lipopeptides, TLR4 recognizes endotoxin (LPS) and pneumolysin (an important pathogenic factor of S. pneumoniae), and TLR9 is activated by bacterial DNA." (PMID 25528768, 2014). "However, whether red blood cells can monitor diseases via TLR9 and mtDNA during bacterial infection remains unclear." (PMID 40046178, 2024). "Studies have shown that TLR2, TLR3, TLR4, TLR7, TLR8, TLR9, and TLR13 within the TLR family can elicit a type I IFN response upon interaction with their specific ligands after bacterial infections (20, –, 26)." (PMID 40525851, 2025). "Typically, during planktonic bacterial infections, macrophages are triggered via the classical pathways of toll-like receptors 2 (TLR-2) and 9 (TLR-9)." (PMID 40006601, 2025). "CpG-rich DNA is enriched in bacterial genomes and therefore TLR9 functions as a sensor for bacterial infection rather than host cell damage." (PMID 37216118, 2023). "Endosomal TLR3, TLR7, TLR8, and TLR9 are specialized in the sensing of nucleic acids produced notably during viral infections or during bacterial infections." (PMID 27057095, 2016). "However, bacterial infections can activate multiple accessory pathways; for example, the receptors NOD1/2, TLR9, and DAI can all be activated in response to bacterial challenge." (PMID 20657826, 2010). "RT-qPCR was performed to explore the expression levels of TLR9, the three components of C1q, arginase, iNOS and IL10 in the WT and NOD mice with or without CpG ODN-simulated bacterial infection." (PMID 27527166, 2016). "Bacterial infection may also account for the previously reported constitutive high expression of TLR1, TLR2, TLR4, and TLR9 but not TLR3 in SGECs from SS patients." (PMID 32208441, 2020).
infectious disease (35 papers, 2009 to 2025). A disorder directly resulting from the presence and activity of a microbial, viral, or parasitic agent in humans. "Of these receptors, TLR9 recognises bacterial and viral DNA containing unmethylated cytosine-phosphate-guanine (CpG) motifs, and variation in TLR9 has been associated with resistance to various infectious diseases." (PMID 34944323, 2021). "Of those, the TLR9 1635A/G polymorphism (rs352140), is most widely studied and shown to be significantly associated with several infectious diseases." (PMID 30651082, 2019). "SNPs in the TLR2, TLR4 and TLR9 polymorphisms have been studied for altering the susceptibility and resistance to various inflammatory and infectious diseases." (PMID 29922617, 2018). "A few genetic polymorphisms within the TLR9 gene have been reported to be associated with a variety of inflammatory and infectious diseases." (PMID 20500814, 2010). "Few genetic association studies have evaluated the linkage between TLR9 SNPs and infectious diseases." (PMID 19924287, 2009). "The purpose of this study is to explore the role of TLR9 as a pattern recognition receptor combined with mtDNA in the monitoring of infectious diseases." (PMID 40046178, 2024). "Numerous infectious diseases, including HIV infections, have been associated with polymorphisms in the TLR9 gene and promoter area, including TLR9 1635A/G and 1486C/T." (PMID 36678440, 2023). "TLR9 agonists have also been investigated as vaccine components against infectious diseases and in anticancer immunomodulation." (PMID 33499143, 2021). "The finding that TLR9 expression is under cis-regulation will strongly pave the path for further studies of infectious diseases, including the consequences of differential TLR9 activation." (PMID 19284650, 2009). "The wide application of TLR9 in this review indicates that it is effective in enhancing targeted immune responses in animals either as vaccine adjuvants or therapeutic agents against infectious diseases." (PMID 39355141, 2024). "Similarly, in monocyte_IFNIC (IFN-inducible monocytes, Cluster 20), the upregulated genes identified in TLR9−/− cells were involved in infectious diseases, lysosomes, antigen presentation and osteoclast differentiation." (PMID 35624094, 2022). "The predominant TLR agonists utilized in animals against infectious diseases was CpG ODN, acting as a TLR9 agonist in mammals, and TLR21 agonists in chickens." (PMID 39355141, 2024). "DNA recognition receptor toll-like receptor 9 (TLR9) and cytoplasmic DNA sensor cyclic GMP-AMP synthetase (cGAS) signalling are critically involved in regulating the functional activities of macrophages in infectious diseases." (PMID 39890818, 2025). "In addition, several studies have mentioned the crosstalk between TLR9 and cGAS-STING in response to DNA damage rerated with infectious diseases and some pathological conditions." (PMID 36176986, 2022). "Furthermore, the gene expression profiles matched those of several infectious diseases including influenza virus infection, and upstream regulator analysis predicted both TLR7 and TLR9 as positive regulators and BTK as a negative regulator of gene expression." (PMID 33240770, 2020). "However, the effect of this intronic SNP in the induction or downregulation of TLR9 expression is not well defined, particularly in the context of infectious diseases." (PMID 24053111, 2013).